CD4 (CD4 molecule)
Diseases named in the same sentence as CD4 in open-access papers (continued):
Sharing a sentence is not in itself a finding about the gene and the disease.
tumor (continued). "Overexpression of IL-9 by the CT26 CRC cell line genetically led to enhanced CD4+ and CD8+ T cell recruitment resulting in heightened serum INFγ and tumour lysis." (PMID 37455828, 2023). "Compared to the PBS control group, MnO2@CPCN plus light treatment increased by 7.7-fold the recruitment of mature DCs (34.7%) and by 5.1-fold and 4.4-fold the infiltration of CD4+ and CD8+ T cells in the tumor tissue, respectively." (PMID 36987269, 2023). "The APCs present tumor antigens through the MHCI or II-peptide complex, which activates CD8+ cytotoxic and CD4+ helper T-cells." (PMID 38002256, 2023). "The DPPA-TRPP/Tab nanoplatform improved the compound's tumor accumulation, suppressed CAFs formation, reduced immunosuppressive cytokine secretion, promoted CD8+ CD4+ T cell infiltration and decreased Tregs distribution, resulting in a potent antitumor effect." (PMID 37064869, 2023). "This immune assessment identifies the effect of the vaccine based on the phenotypes of the CD4+ and CD8+ T lymphocytes and the correlates of tumor control improvement." (PMID 38005965, 2023). "DEX containing MHC I, MHC II, CD86, and HSP70-90 chaperones are capable of triggering the activation of CD4+ and CD8+ T-cell activation, thereby inducing more effective antitumor immunity and addressing the poor immunogenicity of tumor antigens." (PMID 38022585, 2023). "The immunofluorescence results showed that the intratumoural injection of sevelamer significantly promoted the infiltration of CD4+ T and CD8+ T cells in the tumour region, which promoted the effect of immune promotion." (PMID 37471521, 2023). "Our data from tumor cell and CD4+ T lymphocytes co-culture experiments showed that ISG15 can stimulate the differentiation of Th1 subtype CD4+ T cells and a elevated secretion of IFN-γ." (PMID 37217923, 2023). "Within the tumor immune microenvironment, the quantity of CD4+T and CD8+T cells gradually diminishes as the tumor progresses, resulting in an imbalance in immune function and eventual evasion of immune surveillance." (PMID 37881431, 2023). "IL-12 can also induce IFNγ-independent CRC tumour rejection via activation of CD8+ T cells, a process that is dependent on CD4+ T cells and granulocyte-macrophage colony-stimulating factor (GM-CSF)." (PMID 37455828, 2023). "The tumor immune response in cancer microenvironment is comprised of CD8+ cytotoxic T lymphocyte, FOXP3+ CD4+ T regulatory cells, dendritic cells, macrophages, and cytokines." (PMID 36693917, 2023). "CD4 + T cells and CD8 + T cells that contribute to an inflammatory environment act as guardians in anti-tumor immunity." (PMID 36759775, 2023). "HMGB1 can activate TLR2 and TLR4 on dendritic cells (DCs) to initiate antigen presentation and cytokine secretion, activating antigen‐specific CD4+ T cells and CD8+ T cells to recognize and eradicate tumor cells." (PMID 37945630, 2023). "In soft tissue sarcoma model mice, LAG-3 blockade decreased tumor growth and enhanced the secretion of IFN-γ by CD8+ and CD4+ T cells." (PMID 37670328, 2023). "Under oxidative stress induced by X-ray, the presence of T-Fulips increased the number of CD4+ cells, CD8+ cells, and -SH+ cells in the tumor slices." (PMID 37908735, 2023). "The numbers of CD4‐stimulated cDC2s and CD8‐stimulated cDC1s, including resident cDC1s and migratory cDC1s, were significantly increased in tumor and peripheral blood, which suggests that DCs were activated after NE(PD1nb) treatment." (PMID 37565362, 2023). "Our current analytic result indicated that SEMA3G was positively correlated with tumor immune cell infiltration in KIRC, especially CD4+ T cell, macrophage, neutrophil and dendritic cell." (PMID 38070142, 2023). "We next detected IGSF6 expression, CD4+ T cell, CD8+ T cell and CD68+ macrophage cell from pathological tumor specimens with IHC." (PMID 37989761, 2023).
tumor (continued). "According to previous research, pyroptosis-mediated tumor clearance is accomplished through increased immune activation and function, and decrease in CD4+ and CD8+ cell populations hinders tumor regression." (PMID 37056336, 2023). "We also show that the anti-tumour efficacy of olaparib and AZD1775 was dependent on both CD8 and CD4 T cells." (PMID 37582853, 2023). "Tumor microenvironment (TME) analyses in these studies demonstrated enhanced activation of CD8 cytotoxic killer T cells and significant CD4 T cell infiltration." (PMID 37711623, 2023). "We further observed that engagement of both the CD4+ and CD8+ T cell compartments was essential to hamper tumor growth." (PMID 37244905, 2023). "Fusion of viral and tumor antigens into the LC3-II protein of ATG8, which is located in autophagosomal membranes, increases the presentation to CD4+ T cells." (PMID 36936940, 2023). "CD4+CD25+Foxp3+ T cells, regulatory T-cells (T-regs) promote tumor activity by inhibiting the activation of both CD4+ and CD8+ cells." (PMID 37681925, 2023). "Beyond CAR, introduction of a tumor-specific αβ TCR and the corresponding CD4 or CD8 co-receptor for recognition of HLA-restricted tumor antigen in γδ T cells led to their pronounced cytokine secretion and cytolytic effects against leukemia." (PMID 38274800, 2023). "The absence of S100A8 in hematopoietic stem progenitor cells in a specific tumor microenvironment significantly diminished the number of CD8+ T cells and affected the function of CD4+ T cells to some extent, which has some similarity with our results." (PMID 36906583, 2023). "Intratumoral administration of SZU101(another TLR7 agonist) triggers a systemic anti-tumor response and alters the TME by increasing CD4+ and CD8+ cells while reducing Treg cells in a murine breast tumor model." (PMID 37936697, 2023). "Studies have shown that CXCL9 and CXCL10 can directly recruit CD4+ and CD8+ T cells, and NK cells to the tumor site in various cancers." (PMID 38104126, 2023). "CD39 is also upregulated in conventional CD4+ T cells in the TME, which have been shown correlated with impaired anti-tumor activity." (PMID 37287049, 2023). "Recently, high stromal infiltration of CD4 and CD8 in tumor specimens were reported to predict the response to nivolumab treatment in previously treated NSCLC compared to those with low infiltration." (PMID 36662367, 2023). "Administration of MEDI6469 resulted in an increase in the proliferation of tumour-infiltrating T cells, both CD4+ and CD8+, in tumour biopsies before and after surgery in patients with stage III and IV oral head and neck squamous cell carcinoma (OPC)." (PMID 36980527, 2023). "Identical trends for all T cell markers were observed, whereby the density of infiltration by CD3+, CD4+ and CD8+ cells progressively decreased during tumour outgrowth in terms of the total tumour area and within the outer and inner tumour regions." (PMID 37153625, 2023). "l-fuc reduced tumor growth by >50% in control and CD8+ T cell-depleted mice, whereas this effect was completely abrogated by CD4+ T cell depletion (immunodepletion confirmed by splenic profiling)." (PMID 36690875, 2023). "We reported significant elevation in the level of CD4+ and CD8+ T-cell tumour infiltration, with increased CD4+ activation status at D7 post-treatment." (PMID 37153626, 2023). "TMEM123 expression was found in both tumor-infiltrating CD8+ (19% ± 3%) and CD4+ (11% ± 2%) T cells, while it was almost undetectable in T lymphocytes isolated from normal tissues (2.7% ± 0.5%) or PBMCs (0.9% ± 0.2%)." (PMID 37426665, 2023). "Another study showed that LAG-3 expressing CD4+CD25− T-cells are present in the resected tumors and infiltrate metastatic sites more than the primary tumor." (PMID 37509517, 2023). "CD4 + and CD8 + T cells were reported to recognize apoptotic OC antigens and exert an anti-tumor effect." (PMID 37095524, 2023).
tumor (continued). "After coculturing the tumor-lysate-pulsed mDCs and T cells for 5 days, the percentages of OX40-expressing T cells were increased by 29.1, 23.5, and 21.4% among total T cells, CD4+, and CD8+ T cells, respectively." (PMID 38140230, 2023). "In vivo experiments in a xenograft tumor model demonstrated that TAGAP overexpression suppressed tumor growth and promoted CD4+ T cell cytotoxicity." (PMID 37744350, 2023). "BZD also increases the ratio of CD4+ T cells to CD8+ T cells in the spleen and tumor tissues, boosting IFN-γ expression, essential for anti-tumor immunity." (PMID 37799727, 2023). "A limited infiltration of immune cells such as CD3+, CD4+, CD8+, CD19+ cells and Ly6C1 macrophages were observed in the current study, both in untreated and treated KPC tumours." (PMID 38131168, 2023). "These analyses showed that COL10A1 was involved in regulating the immunity of the tumor microenvironment in BLCA, especially in CD4+T cells, CD8+T cells, and M2 macrophages." (PMID 37006317, 2023). "CD4+ T cells can secrete cytokines, such as interferon-gamma (IFN-γ) and tumour necrosis factor-alpha (TNF-α), which directly kills tumour cells." (PMID 38130720, 2023). "Bousso and colleagues show that IFN-γ production is the dominant tumor elimination mechanism exerted by CD4+ CAR T cells and define tumor cell sensitivity to IFN-γ as a determinant of CD4+ CAR T efficacy." (PMID 37248395, 2023). "Expressed on the cell membrane of tumor-infiltrating lymphocytes (TIL), on activated CD4+ and CD8+ T cells, and on regulatory T cells (Treg), LAG-3 binds to MHC-II on APC." (PMID 37484526, 2023). "Remarkably, this effect of Bor appeared specific for CD4+ and CD8+ cells recruited at the tumor site, since the same T populations collected from mice spleens showed no significant changes in the proportion of cells expressing the two markers." (PMID 37069690, 2023). "WGCNA found that 28 genes including CD4 and IL10RA were related to the expression of PTGIS/HRASLS and tumor immune infiltration." (PMID 36703911, 2023). "The immune checkpoint marker PD-L1 and PD-1 and the marker of tumor microenvironment (CD8, CD4, FoxP3) were analyzed in a relevant number of ecSCC." (PMID 37932810, 2023). "In this report, a biopsy of the untreated tumor showed the activation and proliferation of peptide-specific cytotoxic CD8+ T-cell clones and a shift from CD4+ to CD8+ T-cell infiltration." (PMID 37507972, 2023). "Ionizing irradiation of tumor sites showed a 2.5-fold elevation in the percentage of activated CD25+CD8+ memory T cells and a 2-fold increase in activated CD25+CD4+ memory T cells and ICOS+CD4+ TEM in peripheral blood." (PMID 37833255, 2023). "The results showed that compared to the control group, the infiltration of CD3+, CD4+, and CD8+ T cells in the tumor tissue of the BZD group increased while the Ki67 expression decreased." (PMID 37799727, 2023). "The differences in infiltration of CD8+ and CD4+ T cells led to a CD4/CD8 ratio that was high in EO771 tumors, intermediate in B16 tumors, and low in the other tumor models." (PMID 38259467, 2023). "Our study found that the CIBERSORT algorithm showed zero abundance of T cell CD4 naive infiltration, probably because CIBERSORT calculated the relative proportions of immune cell subpopulations in tumor tissues instead of the actual values." (PMID 37600770, 2023). "ICI monotherapies induced the expansion of different tumor-infiltrating T cells (TILs), i.e., PD-1 blockade expanded exhausted-like CD8+ CTLs, whereas CTLA-4 blockade expanded both ICOS+ Th1-like CD4 effectors and exhausted CD8+ CTLs." (PMID 37928556, 2023). "CD11c+ cell clusters residing away from the tumor boundary seemed to incorporate many immune cell niches in their environment, indicated by the expression of CD3, CD4, CD45, CD56, CD20, and CD27 in CD11c+ distant segments." (PMID 38044986, 2023).
tumor (continued). "We performed immunohistochemical staining of CD4, CD8, CCL19, Ki-67, and CD1C in serial sections of the same tumor tissue of BRCA patients." (PMID 36755259, 2023). "For example, model indicators appear to be more effective than the CD4+/CD8+ ratio for predicting Ki67 expression, tumor differentiation and vascular invasion." (PMID 37206348, 2023). "In our human CRC samples, T cells were the predominant population in tumor tissues compared to STM among immune infiltrates analyzed and among T cells, a higher frequency of CD4+ T cells compared to CD8+ T cells was noted (19.1% vs 3.9%)." (PMID 38074634, 2023). "Similar, many questions remain unanswered concerning the cytokines and signaling pathways regulating CD4+ TRM cell development and maintenance in the tumor." (PMID 37545498, 2023). "All these processes subsequently provoke robust CD4+ and CD8+ T cell immune responses, demonstrating that the identical peptide can be a target on tumor cells for immune attack and upon presentation on APCs can start an immune response as well." (PMID 36828830, 2023). "In conclusion, we demonstrated in an in vivo mouse model that all tumor infiltrating cells, including CD4 and CD8 T cells, acquire cytoplasmic material from tumor cells." (PMID 38179041, 2023). "We detected the infiltration of CD4 and CD8T cells in the tumor area by flow cytometry, and the results showed that the infiltration of CD8+T cells was significantly increased after PCMT1 knockdown." (PMID 37596654, 2023). "Compared with lung and peritoneal metastatic tumors, expression of leukocyte (CD45) and T-cell (CD3, CD4, and CD8) markers in liver metastasis were lower in the tumor core but comparable in the peritumoral area." (PMID 37768208, 2023). "REP TILs encompassed a greater abundance of CD4+ than CD8+ T cells, with increased LAG-3 and low PD-1 expressions in both CD4+ and CD8+ T cell compartments compared with the pre-REP TIL and tumor T cells." (PMID 37484198, 2023). "We also unveiled that CD70-targeted cusatuzumab treatment destabilized Tregs in a manner dependent on the CD70 expression level on tumor cells, the CD27 expression level on CD4+ T cells, and the CD4+/CD8+ ratio in the TME." (PMID 37024479, 2023). "Compared with CD4+ Tregs, CD8+ CTLs and other anti-tumor cells have lower adaptability to the TME, are more vulnerable to high ROS and other factors, and become exhausted during tumor development." (PMID 37189453, 2023). "In this study, we examine the expression pattern of cGAS-STING in tumor cells and its effect on the infiltrations of CD8+ and CD4+ T cells, as well as clinical outcomes including survival and recurrence in patients with pMMR/MSS CRC." (PMID 37345163, 2023). "The necrotic tumor tissue after TACE will further stimulate high response to T cells, which can significantly increase the number of CD4+ and CD8+ T cells and improve the immune microenvironment." (PMID 37012542, 2023). "The CD4 and CD8 T cells were more abundant in the tumor area compared to tumor-free tissue (p = 0.034 and p = 0.0002, respectively)." (PMID 36980192, 2023). "Cytotoxic lymphocytes, such as CD8+ and CD4+ cells, alongside their respective cytokine interferon-gamma (IFN-γ), play a significant role as tumor antagonist effectors." (PMID 38328405, 2023). "And we also confirmed that over-expression of ISG15 can increased the number of CD4+ and CD8+ T cells in spleen and the cytotoxicity of tumor-infiltrating lymphocytes in Lewis’s xenograft models." (PMID 37217923, 2023). "Recently, a novel nanomedicine has been constructed that can activate CD4+ T cells and CD8+ T cells and polarize the M2 macrophages to M1 macrophages, which induced potent anti-tumor immunity and has good clinical application prospects." (PMID 36845095, 2023).
tumor (continued). "In other words, SLC35A2 is involved in tumor immune evasion and cancer progression by downregulating the number of activated tumor-infiltrating lymphocytes, such as CD8+ T cells, CD4+ T cells, NK cells, and B cells, and ultimately affecting patient survival." (PMID 37275857, 2023). "We assessed the levels of CD4+ T cells, CD8+ T cells, macrophages, and neutrophils with flow cytometry in the tumor tissues of the treated animals." (PMID 37898619, 2023). "Overall, this analysis suggests that the addition of the vaccine to CAR-T therapy increases the anti-tumor potential of tumor-infiltrating CD8+ T-cells and skews the differentiation of tumor-infiltrating CD4+ T-cells to a Th1 phenotype." (PMID 37413990, 2023). "Consistently, the features for suppression of anti-tumor immunity were dominantly elevated in the CDC20-high group, such as BTLA, CTLA4, CD4, ITGAM, C4B, CD163, and CD206." (PMID 37528490, 2023). "Once recruited to the PDAC TME, CD4+ T lymphocytes are mainly induced to differentiate into anti-inflammatory TH2 cells, which favor tumor development." (PMID 37296886, 2023). "Correlation analyses revealed that ADAM17 was negatively correlated with the purity of the tumour, but positively correlated with the levels of six immune cells, including B cells, CD8+ T cells, CD4+ cells, macrophages, neutrophils, and dendritic cells." (PMID 38069391, 2023). "Infiltration of CD4 T cells is required for activation of CD8 T cells and the tumor responses seen here." (PMID 37868996, 2023). "Immunotyping of single cells isolated from tumor tissues and immunohistochemistry (IHC) analysis revealed that Ascl2 markedly decreased the number of tumor-infiltrating CD8+ T cells, CD4+ T cells, and CD11C+ CD11B- DCs, suggesting immune activation in the TME." (PMID 37591954, 2023). "When CD4+ T cells encounter MHC class II molecules, IFN-γ is released, stimulating host cells to eradicate tumor cells." (PMID 38328405, 2023). "In particular, a significant correlation between the numbers of CD4 and CD8 TILs in tumor/stroma was observed, but, those of stromal CD8 TILs correlated with Foxp3." (PMID 36662367, 2023). "Tumor tissues from HCC patients were probed with anti-ALDOA, anti-CD68, anti-CD163, anti-CD4 and anti-FOXP3 antibodies." (PMID 36937389, 2023). "To minimize bias, we employed a combined approach, considering morphology from H&E slides and the distribution of tumor cells from additional immunohistochemistry staining such as CD3, CD4, CD8, CD7 and CD30." (PMID 37873805, 2023). "A significant increase in CD4+ T-cells and CD8+ T-cells was found in the urine after a single dose of pembrolizumab as well as an increase in infiltrating CD8+ T-cells in the tumor." (PMID 37727793, 2023). "To dissect the individual contribution of CD4 and CD8 T cells to tumor control, we depleted each T cell subset prior to tumor implantation and examined the effects on tumor growth." (PMID 37185301, 2023). "This change in cellular spatial distribution and tumor architecture, as revealed by SOM clustering analysis, is accompanied by inflammatory cell perturbation, with a decrease of CD4+ cells and an increase in CD8+ cells." (PMID 37086293, 2023). "In tumor draining lymph nodes (TDLN), the proportion of CD4+ T cells was reduced while the percentage of CD8+ and NK cells remained unchanged in the GS-PTX-HA-treated animals when compared to the ones treated with GS-PTX." (PMID 36834958, 2023). "CD4+ CTLs, similar to their CD8+ CTL counterparts, express granzymes and perforins to carry out tumor-killing functions." (PMID 37304294, 2023). "In the study of the effect of ICRN on CD4+ and CD8+ T-cells, the results represented that the ratio of tumor infiltration to CD4+ and CD8+ cells was meaningfully enhanced." (PMID 36662090, 2023). "In CLDN18.2-positive tumours, fractions of CD4 + T cells and CD8 + T cells were significantly higher than those in CLDN18.2-negative tumours." (PMID 37582713, 2023).